EGFR (epidermal growth factor receptor)
Diseases named in the same sentence as EGFR in open-access papers (continued):
Sharing a sentence is not in itself a finding about the gene and the disease.
squamous cell carcinoma (continued). "Detection of sensitive mutations in genes, such as EGFR, ALK, and ROS1, is required for advanced non-squamous cell carcinoma of NSCLC." (PMID 35029237, 2022). "NOTCH1 and EGFR have been demonstrated to have antagonistic effects in skin cancer, where suppression of EGFR results in enhanced differentiation of squamous cell carcinoma cells and increased resistance to apoptosis." (PMID 36382054, 2022). "Partial genomic profiling (PCR EGFR and/or FISH/IHC ALK and/or ROS1) was obtained in an additional 23 cases (24%), seven of which were squamous cell carcinomas where EGFR status alone was considered sufficient for treatment decision." (PMID 35108331, 2022). "Understanding the interactions of boron compounds with A431 epidermoid carcinoma cells overexpressing EGFR provides an opportunity to improve the performance of B-ASO delivery without transfection reagents in the treatment of cancer using BNCT." (PMID 36499115, 2022). "We also show that CD109 acts by associating with another protein called the epidermal growth factor receptor (EGFR), stabilizing its levels and promoting its action, leading to increased progression of squamous cell carcinoma." (PMID 35954339, 2022). "In particular, EGFR is expressed in more than 90% of squamous cell carcinomas of the head and neck and is one of the most important therapeutic targets." (PMID 36139779, 2022). "The EGFR (Val592Ile), PIK3CA (Arg19Ile), PIK3CA (Arg852Pro), and ROS (Trp847Leu) mutations were assessed only in patients with squamous carcinoma." (PMID 36422072, 2022). "The clustering approach has also worked for epidermal growth factor receptor (EGFR) magneto-mechanical activation in both A431 epidermoid carcinoma and HeLa cells with high and low receptor expressions, correspondingly." (PMID 36232435, 2022). "In numerous carcinomas, E-cadherin shows tumor-suppressing activities, while in inflammatory breast, ovarian, and squamous carcinomas, E-cadherin has been described to lead to tumor-promoting microembolus formation and prolonged survival via EGFR signaling." (PMID 36010583, 2022). "A phase II trial with monalizumab plus the EGFR inhibitor cetuximab in 40 patients with squamous cell carcinoma of the head and neck resulted in a response rate of 31%." (PMID 35628346, 2022). "For the first time, we show that human sera can rescue squamous carcinoma cells from growth suppression mediated by EGFR-targeted drugs." (PMID 33748471, 2021). "Epidermal growth factor receptors (EGFRs) and/or EGFR downstream signalling cascades have long been understood as essential for the development of squamous cell carcinomas." (PMID 34944837, 2021). "Almost all patients with EGFR-positive NSCLC had adenocarcinomas (386 patients [99.2%]) whereas 56 patients with wildtype EGFR NSCLC (16.8%) had squamous cell carcinoma (P < .001)." (PMID 34739062, 2021). "Interim results of a phase II trial combining monalizumab with the epidermal growth factor receptor (EGFR) inhibitor cetuximab in patients with squamous cell carcinoma of the head and neck have also shown a 31% objective response rate." (PMID 33924213, 2021). "Diagnostic workup led to diagnosis of T4N3M1b squamous cell carcinoma (SCC), epidermal growth factor receptor (EGFR) and anaplastic lymphoma kinase (ALK) mutations negative." (PMID 34275518, 2021). "High frequency of mutations in HRAS, copy number alterations and aberrant expression levels in KRAS, NRAS, MYC and EGFR have been reported in relation with development of many squamous cell carcinomas." (PMID 34796107, 2021). "More than 80% of the squamous cell cancers of the head and neck have over expression of the epidermal growth factor receptor (EGFR) which correlates with locoregional failure, distant metastases, and poor prognosis." (PMID 34104833, 2021).
squamous cell carcinoma (continued). "All patients had stage IV disease, adenocarcinoma and squamous cell carcinoma were the most common histological types (accounting for 40.54 and 56.08%, respectively), and EGFR wild-type patients accounted for 49.32% of the cases." (PMID 34976813, 2021). "EGFR activation by EGF also leads to E-cadherin internalization in A431 epidermoid carcinoma cells and A549 lung cancer cells via caveolae." (PMID 35127732, 2021). "Given the higher level of EGFR in squamous cell carcinoma comparing with adenocarcinomas which made up the bulk of the non-immune class, EGFR was significantly enriched in immune class comparing with non-immune class." (PMID 33971902, 2021). "We demonstrate that human serum antagonizes the effects of EGFR-targeted drugs erlotinib and cetuximab on A431 squamous carcinoma cells by increasing IC50 by about 2- and 20-fold, respectively." (PMID 33748471, 2021). "EGF-induced NF-κB activation was observed in A431 cells, an epidermoid carcinoma cell line expressing high levels of EGFR." (PMID 34769306, 2021). "Using human squamous carcinoma cell line A431, we show the impressive modulation of activities of two EGFR-specific drugs by human blood serum." (PMID 33748471, 2021). "A431 squamous carcinoma cells have high levels of endogenous EGFR expression, and provide a model for tumors with high EGFR expression and modest levels of RON." (PMID 34821550, 2021). "Of note, CCAT1 has been linked to SOX2 as a coactivator in squamous cell carcinoma, and CCAT1 binds to epidermal growth factor receptor (EGFR) super-enhancer to stimulate EGFR expression by forming a complex with TP65 and SOX2." (PMID 33952719, 2021). "In this work, we analyzed the assembly of tripeds 1 and 2 in detail and screened the nucleolytic stability and silencing properties of nanostructures 1/2 towards endogenous EGFR in the human squamous carcinoma cells (A431)." (PMID 34064412, 2021). "Alkannin can also cause cell-cycle arrest and induce apoptosis by regulating the EGFR-NF signaling pathway in human epidermoid carcinoma A431 cells." (PMID 34876915, 2021). "Squamous cell carcinomas of the head and neck showed a high expression of epidermal growth factor receptor (EGFR)." (PMID 32942549, 2020). "Notably, the squamous lineage of these lesions is identical to squamous carcinomas in other anatomical locations and its hallmark is the robust positive staining for p63, p40, and K5/14 in all cases, with coexpression of the EGFR in 94.7%, and variable staining for the squamous keratins K10/13." (PMID 32170368, 2020). "Our findings are in line with a vast number of earlier studies, where delivery of decorin via an adenovirus vector into the tumor cells inhibited the growth of lung, colon, and squamous cell carcinomas by attenuating EGFR phosphorylation." (PMID 32477937, 2020). "We showed that MNT with affibody on the N-terminus (MNTN-affibody) effectively delivered the Auger electron emitter 111In to target cell nuclei and had pronounced cytotoxic efficacy against EGFR-overexpressing human A431 epidermoid carcinoma cells." (PMID 32194412, 2020). "PCI of rGel-EGF was highly effective against EGFR-expressing squamous cell carcinoma cells (SCC-026 and A-413) and even against cell lines resistant to the EGFR inhibitor cetuximab." (PMID 31936595, 2020). "Squamous cell cancer of the lung is rich in epidermal growth factor receptors (EGFR) with a 2.5-fold amount than that of normal skin." (PMID 33324524, 2020). "Malignant as well as premalignant lesions can overexpress EGFR, with 40–80% of NSCLC patients being identified with abnormal expressions of EGFR (increased gene copy number per cell), with the highest rates seen in squamous cell carcinomas." (PMID 33198090, 2020).
squamous cell carcinoma (continued). "A431 squamous carcinoma cells have been shown to express high levels (i.e., ~1 × 106 molecules per cell) of epidermal growth factor receptor (EGFR) on the cell surface." (PMID 31969631, 2020). "Histologic transformation to squamous cell carcinoma is a mechanism of EGFR inhibitor resistance in EGFR mutant NSCLCs." (PMID 32822576, 2020). "This cancer vaccine prevents the growth of squamous cell carcinoma expressing epidermal growth factor receptor (EGFR) vIII and induces EGFR vIII-specific cellular immunity." (PMID 32522267, 2020). "The binding of MNT to EGFR was evaluated with an EGFR-expressing human A431 epidermoid carcinoma cell line." (PMID 32194412, 2020). "Treatment of the epidermoid carcinoma cell line A431, widely known for its dramatic overexpression of wild-type EGFR, resulted in decreased cellular proliferation and migration." (PMID 32050662, 2020). "We have reported that HIV+ exosomes stimulate the proliferation and proto-oncogene expression of squamous cell carcinoma cells in an EGFR-dependent manner." (PMID 32051269, 2020). "Some researches revealed the presence of squamous cell carcinoma (SCC), wild-type EGFR or KRAS gene mutations was associated with high expression of PD–L1, providing potentially benefits for the administration of PD-1/PD–L1 blockade in lung cancer." (PMID 32587276, 2020). "This malignant growth antibody forestalls the development of squamous cell carcinoma communicating epidermal growth factor receptor (EGFR) vIII and instigates EGFR vIII-explicit cell insusceptibility." (PMID 33193429, 2020). "Over 90% of all head and neck cancers are squamous cell carcinomas, and 90%–100% of head and neck squamous cell carcinomas (HNSCCs) overexpress epidermal growth factor receptor (EGFR)." (PMID 33204681, 2020). "The epidermoid carcinoma cell line A431 is amplified for wild-type EGFR and is often used as a model system to study EGFR signaling." (PMID 32234966, 2020). "We used the human vulva epidermoid carcinoma cell line A431 because these cells express high levels of wild-type EGFR and respond strongly to EGF stimulation." (PMID 32053105, 2020). "Our male patient was an unusual case of synchronous double primary NSCLC with EGFR L858R mutations in adenocarcinoma and EML-4ALK rearrangement in squamous cell carcinoma." (PMID 32727606, 2020). "EGFR is overexpressed in up to 74% of bladder cancer tissue specimens, and is amplified in squamous cell carcinomas (SCC) of the bladder." (PMID 33334367, 2020). "The epidermal growth factor receptor (EGFR) is up-regulated on most squamous cell carcinoma cells and dysplastic precursor lesions and has been identified as a drug target for immunotherapy." (PMID 31561451, 2019). "In summary, the present study demonstrated that patients with squamous cell carcinoma should also be routinely tested to determine their EGFR and ALK gene statuses." (PMID 31144459, 2019). "In conclusion, we generated an EGFR-directed fully human antibody with low toxicity that can inhibit squamous cell carcinoma and colon cancer tumor growth in xenograft mice." (PMID 30733972, 2019). "In our animal studies, an anti-EGFR affibody probe was able to image metastatic squamous carcinoma cells in lymph nodes." (PMID 30669481, 2019). "Bucillamine restored EGFR kinase activation in vitro and EGFR signaling in human epidermoid carcinoma A431 cells." (PMID 31703435, 2019). "Overexpression of epidermal growth factor receptor (EGFR) occurs in approximately 80% of patients with adenocarcinoma and squamous cell carcinoma, and many studies have demonstrated that overexpression of EGFR is associated with a lower survival rate." (PMID 31354907, 2019). "This proposed technique is built upon the knowledge that 90% of squamous cell carcinomas in the head and neck have upregulated EGFR." (PMID 31998640, 2019).
squamous cell carcinoma (continued). "In epidermoid carcinoma (A431) cells and breast tumor samples LynA Y32 is phosphorylated by the epidermal growth factor receptor (EGFR), allowing it to phosphorylate MCM-7 and stimulate cell proliferation." (PMID 31282857, 2019). "For example, over 90% of all HNCs are pathologically squamous cell carcinomas, and 80–100% of HNCs feature epidermal growth factor receptor (EGFR) overexpression." (PMID 30700700, 2019). "EGFR is overexpressed in approximately 90% of squamous cell carcinomas of the head and neck, and more than 80% of NPC patients overexpress EGFR; moreover, its expression is associated with unfavorable T stage and overall survival." (PMID 31744469, 2019). "The present study revealed that although adenocarcinoma was the most common pathological type to be submitted for EGFR/ALK evaluation, patients with squamous carcinoma had an EGFR mutation rate of 8.3% and an ALK rearrangement rate of 3.7%." (PMID 31144459, 2019). "The binding of E07 to EGFR expressing A431 epidermoid carcinoma cells led to inhibition of EGFR autophosphorylation and cell proliferation in three-dimensional cultures." (PMID 29562664, 2018). "As a consequence of inconsistency in methods of evaluation of EGFR, incongruity exists between studies reporting EGFR as a prognostic marker of squamous cell carcinoma." (PMID 29954411, 2018). "This CPP targeted the human squamous carcinoma A431 cells through an interaction with the epidermal growth factor receptor (EGFr)." (PMID 29855618, 2018). "They treated human squamous carcinoma NA cells with hydrogen peroxide (0~ 1 mM) and found that hydrogen peroxide enhanced EGFR phosphorylation." (PMID 29548337, 2018). "It is of note that EMT can be also triggered by anti-EGFR huAb therapy in squamous cell carcinoma of the head and neck." (PMID 29515580, 2018). "We showed that Pan-ICG is promising as an activatable probe for use in the detection of lymph node metastases in EGFR-positive squamous cell cancer of the lung." (PMID 29856819, 2018). "The binding capacity of 7D12 was first tested in A431 cells because the 7D12 nanobody was constructed by immunizing a Llama with EGFR overexpressing A431 epidermoid carcinoma cells." (PMID 30348204, 2018). "Further studies are needed to better understand the regulatory mechanisms of EGFR overexpression and its downstream signaling pathways in BC, particularly in the context of squamous cell carcinoma (SCC) and transitional cell carcinoma (TCC)." (PMID 30413194, 2018). "Tumor targeting 131I-labelled anti-EGFR-antibody (Cetuximab) was used in the prototypic EGFR-expressing A431 human squamous cell carcinoma xenograft model." (PMID 30042828, 2018). "On the other hand, we suggest that molecular studies should be performed in squamous cell carcinoma of head and neck in our setup to identify patients that can avail response from anti-EGFR therapy." (PMID 29954411, 2018). "Expression of EGFR in a number of epithelial cell tumors in humans has been well documented, and 80% of squamous cell carcinomas are marked by over-expression of EGFR, resulting in proliferation and differentiation of keratinocytes." (PMID 29954411, 2018). "PTPRS was reported to be an EGFR phosphatase in A431 epidermoid carcinoma cells and head and neck cancers." (PMID 29915291, 2018). "A previous report showed that c‐fos expression changed in human squamous cell carcinomas after EGFR‐TKI treatment and correlated with therapy response in xenograft models." (PMID 30361264, 2018).
squamous cell carcinoma (continued). "In conclusion, EGFR signaling in squamous cell carcinoma cells from the head and neck represses the production of several IFNγ/TNFα-induced T-cell attracting chemokines." (PMID 30192802, 2018). "On the other hand, we suggest that molecular studies should be performed in squamous cell carcinoma of head and neck in our setup to identify patients that can benefit from anti-EGFR therapy." (PMID 29954411, 2018). "A-431 is an epidermoid carcinoma with the highest EGFR expression where DLD-1 is a Duke’s type C. colorectal adenocarinoma with intermediate EGFR expression." (PMID 29464066, 2018). "The down-modulation of both p-EGFR and total EGFR total contents by D609 were also observed in human squamous carcinoma cell lines." (PMID 28423060, 2017). "Previous studies showed that c-Src kinase activity inhibition sensitizes cancer cells to EGFR inhibitors in epidermoid carcinoma cell lines and NSCLC cell lines." (PMID 29132432, 2017). "It had shown that differential EGFR-signaling promoted anchorage-independent growth of squamous carcinoma cells." (PMID 28977882, 2017). "First, we evaluated EGFR expression status by immunohistochemistry (IHC) in 70 tumor specimens from Chinese EC patients, including 65 squamous-cell carcinoma, 2 adenocarcinoma, 2 small-cell carcinoma and 1 sarcoma." (PMID 28881608, 2017). "14E1 was isolated from mice immunized with A431 epidermoid carcinoma cells and recognizes both wild-type EGFR and EGFRvIII." (PMID 28752098, 2017). "CDC was not induced in H292 and A549 with imgatuzumab or cetuximab, whereas a CDC response was observed in EGFR-amplified squamous-cell carcinoma A431 cells as positive control." (PMID 28467975, 2017). "VEGF increase in vivo can result from EGFR blockage not only by erlotinib but also by antibodies, as shown for squamous cell carcinoma." (PMID 28915658, 2017). "Cetuximab (Erbitux®) is an anti-epidermal growth factor receptor (EGFR) MAb approved for the treatment of metastatic colorectal cancer and squamous cell carcinoma of the head and neck." (PMID 29088859, 2017). "Cox proportional hazards models showed univariate associations (P < 0.2) between poor PFS and five factors; Positive-sHGF at response-evaluation, ECOG performance status (PS), EGFR-WT (or squamous cell carcinoma), second-line treatment, and monotherapy." (PMID 29069748, 2017). "To further confirm the results obtained in the NIH3T3 murine model cell line, we moved our interest on human epidermoid carcinoma cell line A431 that endogenously overexpresses the EGFR." (PMID 27732953, 2016). "Studies using antibodies against EGFR have had some success in combination with radiotherapy against squamous cell carcinoma of the head and neck." (PMID 26784176, 2016). "In other epithelial derived cancers that generally express wild-type EGFR like squamous cell carcinomas, breast and prostate cancers, response rates to EGFR-TKIs are generally less than 5 %." (PMID 27036206, 2016). "The A431 vulval epidermoid carcinoma cell line overexpressing EGFR exhibited a significant response to an EGFR–TKI (gefitinib) but became resistant when co-treated with IGF-I13." (PMID 26725982, 2016). "The two patients with the greatest decrease in metabolic activity as determined by change in FDG-avidity had EGFR wild-type NSCLC (squamous carcinoma subtype)." (PMID 27028852, 2016). "14E1 was isolated from mice immunized with A431 epidermoid carcinoma cells as an EGFR-binding antibody with nine-fold higher affinity for the extracellular domain of EGFR than cetuximab." (PMID 27153091, 2016).